MUC1 (mucin 1, cell surface associated)
Diseases named in the same sentence as MUC1 in open-access papers (continued):
Sharing a sentence is not in itself a finding about the gene and the disease.
ovarian carcinoma (continued). "We previously reported that anti-MUC1 monoclonal antibody C595 (MAb C595) plus docetaxel (DTX) increased efficacy of DTX alone and caused cultured human epithelial ovarian cancer (EOC) cells to undergo apoptosis." (PMID 21931707, 2011). "B-cells from tumor draining lymph nodes from ovarian cancer patients produce abs that react with the MUC1 protein core." (PMID 24212946, 2011). "HMFG1 is a murine monoclonal antibody with specificity to MUC1, a cell surface glycoprotein that is expressed by more than 90% of epithelial ovarian cancer and other tumors." (PMID 20146807, 2010). "For instance, sialyl-T on MUC1 suppresses ovarian cancer cell seeding at the peritoneal site." (PMID 40885395, 2025). "The MUC1.Tg mouse model we used is an established replica which mimics human ovarian cancer." (PMID 38339228, 2024). "Ovarian cancer cells’ metastasis, progression, and treatment resistance might also be attributed to MUC1." (PMID 38540735, 2024). "However, the efficacy of the proposed system should be extensively investigated in the in vivo models of MUC-1-expressing ovarian cancer." (PMID 36615606, 2023). "Therefore, in the present study, to improve the effectiveness of SUN, MMSNP armed with MUC-1 aptamer was used for active targeted drug delivery to the ovarian cancer cells." (PMID 36615606, 2023). "Another hypothesized MOA for talc and ovarian cancer is through decreased anti-MUC1 antibodies; however, the available information supporting this MOA is sparse." (PMID 37608907, 2023). "The report shows that MUC1-TRIM46-KRTCAP2 mRNA is not expressed in non-cancerous ovaries and its fusion protein localizes to cytoplasm without glycosylation in ovarian cancer cells, which is a similar feature of tumor-associated MUC1." (PMID 35054873, 2022). "Third, expression profiles of three sialidases in ovarian cancer cell lines suggest that sialylation of MUC1 oligosaccharides might modulate MUC1-dependent alteration of growth and other behaviors in vitro and in vivo." (PMID 34641504, 2021). "Thus, sialylation of MUC1 appears to be the key element in reducing peritoneal dissemination and implantation and promoting ascites formation by ovarian carcinoma cells." (PMID 34641504, 2021). "Other than MUC16, ovarian cancer cells also overexpress MUC1, MUC9, and MUC13." (PMID 32785160, 2020). "Additional PET imaging experiments in mice bearing orthotopic MUC1-expressing ovarian cancer xenografts likewise demonstrated that [89Zr]Zr-DFO-AR20.5 enables the visualization of tumor tissue—including metastatic lesions—with promising tumor-to-background contrast." (PMID 32429033, 2020). "Magnetic beads coated with antibodies for the epithelial markers EpCAM, HER2, and MUC1 were applied to enrich CTCs in samples from patients with ovarian cancer, which were followed by multiplex RT-PCR for six genes (EpCAM, HER2, MUC1, WT1, P16, and paired box gene 8)." (PMID 33327605, 2020). "One such mucin, MUC1, is known to play a key role in ovarian cancer." (PMID 32075174, 2020). "MUC1 dendritic cell vaccine, that introduces cellular immune response against MUC1, was tested in Phase I/II clinical trial in the treatment of various advanced malignancies, including ovarian cancer." (PMID 32785160, 2020). "The role of MUC1 in ovarian cancer provides a representative case." (PMID 32429033, 2020). "Once the presence of EpCAM positive CTCs in the blood of patients was confirmed using two methodologies, an expression profile analysis, including a panel of genes related to cell plasticity and ovarian cancer aggressiveness (MUC1, CK19, CXCR4, TIMP1, ALDH1, CD24, CD44, GDF1), was carried out." (PMID 32423054, 2020). "The most commonly described aptamer MUC1 named S2.2 binds with high affinity to abnormally glycosylated mucin-1, a cell surface glycoprotein, which expresses in many cancers, such as breast, colon, lung, and ovarian cancers." (PMID 30943985, 2019).
ovarian carcinoma (continued). "In summary, we found that circWHSC1, which is highly expressed in ovarian cancer, can adsorb miR-145 and miR-1182, up-regulates the expression of downstream targets MUC1 and hTERT, promotes cancer cell proliferation and invasion, also can be secreted into exosomes." (PMID 31666098, 2019). "The oncogenic MUC1, a member of the class of epigenetically controlled genes, is a transmembrane protein that is aberrantly overexpressed and confers poor prognosis in a variety of cancers, including pancreatic, colorectal, breast, lung and ovarian cancer." (PMID 30518424, 2018). "We also employed a highly aggressive ovarian cancer cell line Skov3 to examine MUC1 expression." (PMID 30518424, 2018). "Representative images of STON2 and MUC1 staining in ovarian cancer tissues are shown." (PMID 30518424, 2018). "This suggests that MUC1 acts downstream of STON2 in ovarian cancer cells." (PMID 30518424, 2018). "We utilized a cytoplasmic truncation of MUC1 (MUC1ΔCT), the mucin most commonly overexpressed in breast and ovarian cancers, to limit any cytoplasmic signaling which might confound our results." (PMID 29266001, 2017). "Thus, it is very unlikely that GALNT6 enhances the aggressive phenotypes of ovarian cancer cells through the MUC1 pathway." (PMID 28388560, 2017). "Additionally, MUC1 aptamer was able to specifically deliver let-7i miRNA to ovarian cancer cells, rendering these cells more sensitive to paclitaxel." (PMID 26863567, 2016). "Furthermore, the overproduction of MUC1 in ovarian cancer leads to the increased circulating serum MUC1 levels detectable by standardized ELISA tests." (PMID 26492273, 2015). "For MUC1, none of the polymorphisms we tested were significantly associated with overall ovarian cancer risk in the per allele model." (PMID 24551091, 2014). "We genotyped germline variants of MUC16 (rs2547065, rs1559168, rs12984471, rs2121133) and MUC1 (rs2070803, rs4072037, rs1045253) using samples collected from 758 ovarian cancer cases and 788 controls enrolled in the New England Case-Control Study between 2003 and 2008." (PMID 24551091, 2014). "MUC1 (CA153) can be used to predict chemoresistance to cisplatin in ovarian cancer." (PMID 23708102, 2013). "Blocking MUC1 can improve the sensitivity of ovarian cancer cells to paclitaxel and doxorubicin, as the anti-apoptotic effects of MUC1 on oxidative stress-induced apoptosis and genotoxic agent-induced apoptosis have been correlated to its chemoresistant mechanisms." (PMID 23708102, 2013). "Overexpression of MUC1 has been reported in ovarian cancer, but the information is limited due to small numbers and the correlation between overexpression and prognosis remains unclear." (PMID 23241107, 2012). "Lastly, several cancers, including ovarian cancers, over-express the surface glycoprotein MUC1." (PMID 22587442, 2012). "MUC1 is overexpressed on 90% of early ovarian cancer cell surfaces." (PMID 22235224, 2011). "Thus, MUC1 has been recognized as a promising molecular target for immunotherapy in patients with ovarian cancer." (PMID 22235224, 2011). "Circulating MUC1 IgM abs reactive with the MUC1-N protein core are present in breast, colon and pancreatic cancer patients, as well as in healthy women and benign and malignant ovarian tumor patients." (PMID 24212946, 2011). "MAL2 overexpression might also reduce cytoplasmic MUC1 accumulation, which has been indicated to be an adverse finding in breast and ovarian carcinomas, tumor types which also overexpress MAL2." (PMID 19175940, 2009). "However, the regulatory mechanisms of MUC1 in ovarian cancer remain elusive." (PMID 30518424, 2018). "However, clinical results from a Phase I clinical trial including 25 patients with CEA- or MUC1-expressing metastatic cancers who had progressive disease following standard chemotherapy (three of them with ovarian cancer) showed limited evidence of clinical activity." (PMID 28536377, 2016).
ovarian carcinoma (continued). "Since many types of ovarian cancer cells express high levels of (MUC1) on their cell surface, the imaging strategy is using SPIONs and their attachment to monoclonal antibody that binds to the MUC1 for enhancing the contrast of MUC1-expressing ovarian cancer cells." (PMID 24194685, 2013). "However, in vitro studies on ovarian cancer cell lines were able to show increased sensitivity to docetaxel when combined with the monoclonal antibody MAb C595 and in vivo studies using a MUC1/docetaxel conjugate showed higher cytotoxicity than docetaxel alone in multidrug resistant ovarian cancer." (PMID 23241107, 2012). "In the ovarian cancer study, we observed that the expression levels of ERBB3 and MUC1 were higher in mucinous and clear cell carcinoma than in serous and endometrioid carcinoma." (PMID 40046734, 2025). "In fact, several MUCs are currently used as biomarkers in the clinic, such as MUC1 (CA15-3) in breast cancer and MUC16 (CA125) in ovarian cancer." (PMID 40885395, 2025). "Western blot analysis of extracts from A2780 ovarian cancer cells and parental RPE-1 cells using the VNp-anti-Muc1 as primary antibody revealed a discrete band which migrated at a size consistent with Muc-1 protein." (PMID 39965660, 2025). "In a phase 1/2 clinical trial, anti-MUC1 CAR NK cells were derived from a NK-92 cell line to treat lung, pancreatic, colon, and ovarian cancers, with a specific focus on tumors co-expressing PD-L1 and MUC1 (NCT02839954)." (PMID 40149002, 2025). "While MUC1, MUC4, MUC15, MUC16, MUC17, and MUC21 are all potential candidate biomarkers for glioma, the extensive research on MUC1 and the current clinical application of MUC16 in ovarian cancer highlights their promise as therapeutics for glioma." (PMID 39767713, 2024). "M1231, a joint venture between Merck and Sutro Biopharma, is a bsADC targeting EGFR and mucin 1 (MUC1), which are highly co-expressed in cancers such as NSCLC, esophageal squamous cell carcinoma, HNSCC, TNBC, and ovarian cancer." (PMID 39065587, 2024). "For example, vaccination with autologous DCs targeting Mucin 1 (MUC1), a glycoprotein highly expressed in ovarian carcinomas, resulted in a strong MUC1-specific T cell response and prolonged survival in patients with advanced OC." (PMID 38164130, 2023). "Other transcripts that were upregulated during ovarian cancer spheroids formation include DACH1, the Discoidin domain receptor (DDR1), the winged helix transcription factor Forkhead box P1 (FOXP1), and MUC1." (PMID 37189618, 2023). "We propose that targeting ovarian cancer cells, using SUN-loaded MMSNPs and conjugated to MUC-1 aptamer, would improve its anti-cancer effect." (PMID 36615606, 2023). "Mucin 1 (MUC1), also known as CA153, is one of the commonly used tumor markers in the diagnosis and recurrence monitoring of ovarian cancer." (PMID 33718143, 2021). "In an attempt to explore the significance of CTC markers in ovarian cancer, we investigated the expression of EPCAM, MUC1, CEA, HE4 and CA125 mRNAs." (PMID 34006887, 2021). "In ovarian cancer, mucins MUC1, MUC5AC, MUC6 and MUC16 are carriers of TF antigen; among them, MUC1 is a natural ligand for Gal-3." (PMID 32486344, 2020). "These include those from cultured cells (MUC1 from breast cancer and chronic myelogenous leukaemia cell lines, and MUC16 from a cervical cell line), and ascites from ovarian cancer patients." (PMID 32937961, 2020). "From them, CK19, MUC1, CD24, CD44, TIMP1, and CXCR4 appeared, characterizing the ovarian cancer circulating population." (PMID 32423054, 2020). "MUC1 and MUC4 overexpression induces the EMT in renal carcinoma and ovarian cancer via the Wnt/β-catenin pathway, whereas MUC16 knockdown induces EMT." (PMID 32825724, 2020). "Similar to MUC1, the cancer testis antigen NY-ESO-1 is a vaccine target in epithelial ovarian cancer, promoting induction of tumor-specific humoral and cellular responses." (PMID 30646939, 2019).
ovarian carcinoma (continued). "STn is found on a significant number of ovarian cancers and is expressed on the well-known ovarian cancer biomarker CA-125 (MUC16), as well as on MUC1, and is rarely present on normal tissue." (PMID 30052649, 2018). "High expression of TAG72, MUC1, and MUC16 has been shown in ovarian cancer patient tissue samples, with nearly 100% of ovarian cancers identified with simultaneous staining of the three antigens." (PMID 30510550, 2018). "Since TAG72, MUC1, and MUC16 have all been identified as potential targets in ovarian cancer, we first assessed expression of these cell surface antigens on TAG72-negative OVCAR8, and TAG72-positive OVCAR3 and OV90 cells." (PMID 30510550, 2018). "Expression analysis of MUC1, MUC16, and TAG72 on patient samples from various epithelial subtypes of ovarian cancer highlights antigen heterogeneity in this disease and demonstrates the aberrant expression pattern of cell-surface glycoproteins." (PMID 30510550, 2018). "Further random examinations of specimen sections from the paraffin-embedded blocks of ovarian cancer patients confirmed that STON2 and MUC1 expression correlated negatively." (PMID 30518424, 2018). "Our findings suggest that STON2 depression up-regulates MUC1 expression, along with inhibition of DNMT1, in a process that contributes to the maintenance of stem-like properties in ovarian cancer cells." (PMID 30518424, 2018). "Cell-derived extracellular vesicles were purified by ultracentrifugation from ovarian cancer ascites fluid and from the supernatant of the MUC1-DG75 cell line, a lymphoblastoid cell line engineered to express MUC1 also in the MVs." (PMID 28993771, 2017). "Other interesting markers are MUC1, EGFR and CD142, which are all highly related to cancer, particularly ovarian cancer." (PMID 28936249, 2016). "We used two mouse cancer cell lines stably transfected with human MUC1 cDNA, the lymphoma cell line RMA (RMA-MUC1) and the mouse ovarian cancer cell line IG10 (IG-10/MUC1), as well as the human colon cancer cell line Caco-2 that spontaneously expresses MUC1." (PMID 25675408, 2015). "In ovarian cancer patients, a benefit in survival was observed after intraperitoneal administration of radiolabelled HMFG1, a murine monoclonal antibody to MUC1." (PMID 24212946, 2011). "For example, immunohistochemistry of a combination of MUC1, VEGF and other two molecules was detected all ovarian cancer." (PMID 20492722, 2010). "Recently, several molecules other than mesothelin have been found to be potential biomarkers for ovarian carcinoma, such as DF3, vascular endothelial growth factor, MUC1, HE4, and CA19-9." (PMID 19293794, 2009). "It has been reported that the Lewis y antigen was expressed on a number of different molecular carriers, including 2 major ovarian cancer antigens (CA125 and MUC-1), suggesting the high incidence of Lewis y in ovarian cancer." (PMID 20003467, 2009). "Therapeutic efficacy of anti-MUC1 MAb (HMFG1: anti-human milk fat globules) radiolabeled with 90Y, 186Re and 131I was investigated in an OVCAR3 ovarian cancer xenograft model." (PMID 20034397, 2009). "In addition, T cell immunity and B cell immune responses to selected epitopes of MUC1 from ovarian, breast, pancreatic and colon cancer patients have been demonstrated, as have circulating immune complexes to MUC1 in the serum of breast and ovarian carcinoma patients." (PMID 16776849, 2006). "Examples of EVs-related proteins in the context of ovarian cancer tumor biomarker detection include CD9, MUC1 (detected by aptamer-conjugated spiky Au@Fe3O4), and simultaneous detection of various markers like CD63, EpCAM, CD24, and CA-125 to avoid false positives." (PMID 40277517, 2025). "Specifically, authors quantified anti-MUC1 antibodies in women serving as controls in an ovarian cancer study (no cases were evaluated for anti-MUC1 antibodies)." (PMID 37608907, 2023).
ovarian carcinoma (continued). "Eleven trials are about solid tumors (including ovarian cancer, prostate cancer, non-small cell lung cancer, pancreatic cancer, and glioblastoma), in which CAR-NK cells target some over-expressed antigens such as MUC1, PSMA, ROBO1, mesothelin, and HER2." (PMID 36324149, 2022). "Additionally, the first clinical trial of CAR-NK therapy for solid tumor treatment used MUC-1 CAR-NK cells to target against multiple malignant solid tumors, e.g., glioblastoma, pancreatic, colorectal, breast and ovarian cancer (NCT02839954)." (PMID 36324149, 2022). "TNF, ESR1, MUC1 are HOUP genes, suggesting a potential role in ovarian cancer progression." (PMID 32192517, 2020). "In fact, MUC family member has been viewed as ideal target for CAR‐T cells in various cancers: CAR‐T cell therapy specific for MUC1 has been clinically tested in HCC, breast and glioma 25; CAR‐T cells specific for MUC16 have also being investigated in ovarian cancer." (PMID 32596961, 2020). "Moreover, knockdown of the glycosyltransferase responsible for synthesis of MUC1 and MUC13, N-acetylgalactosaminyltransferase 3 (GALNT3) and GALNT14, respectively, reduces migration of ovarian cancer cells." (PMID 32785160, 2020). "MUC1 is highly expressed in ovarian carcinoma but not in ovarian surface epithelium (OSE) and serous cystadenomas." (PMID 32075174, 2020). "TNF, ESR1, MUC1 and FOXO1 are our candidate genes that might take part in ovarian cancer progression in an epigenetic approach, TNF, ESR1 and FOXO1 may serve as potential markers for ovarian cancer prognosis evaluation." (PMID 32192517, 2020). "The downregulation of the MUC1 protein, observed in our study upon knocking down both the GALNT3 and GALNT6 genes, emphasizes its possible role in enhancing the malignant phenotype of ovarian cancer." (PMID 31071912, 2019). "Taken together, these observations provide evidence that STON2 acts as a negative modulator via the MUC1-mediated pathway in ovarian cancer." (PMID 30518424, 2018). "In summary, we observed for the first time that STON2 acts as a negative modulator in ovarian cancer cells via DNMT1/MUC1-mediated epigenetic mechanisms." (PMID 30518424, 2018). "Polymorphic epithelial mucin (PEM, or MUC1 with different epitopes: CA 15.3 and CA 27.29) and MUC16 (CA 125) are the most extensively studied MUCs, although the latter is more frequently used for ovarian cancer than for BC." (PMID 26133558, 2015). "In ovarian cancer, a promising TAA for DC vaccines is mucin 1 (MUC-1)." (PMID 25806106, 2015). "Only the aberrantly glycosylated MUC1 is found to be over-expressed in ovarian cancer, whereas normal ovarian surface epithelium and serous cystadenomas do not express these epitopes." (PMID 23241107, 2012). "Concentrations of MUC1 IgM abs in healthy women were inversely correlated to age, and were higher than in ovarian cancer patients, regardless of age." (PMID 24212946, 2011). "At present, MUC1 and MUC16 are the best and only characterized mucins and monoclonal antibodies against MUC1 and MUC16 are under preclinical and clinical investigations for ovarian cancer treatment." (PMID 20034397, 2009). "Second, we have previously demonstrated that survival of clear cell-type ovarian cancer cells under anoikis conditions was enhanced by MUC1 expressed on the cell surface, thus adhesion may not be necessary for MUC1-positive tumor cells to survive." (PMID 34641504, 2021). "Hub genes including TNF, ESR1, MUC1 and FOXO1 might be potential targets for diagnosis or treatment of ovarian cancer in an epigenetic approach, TNF, ESR1 and FOXO1 may serve as potential markers for ovarian cancer prognosis evaluation." (PMID 32192517, 2020).